PFKL (phosphofructokinase, liver type)
Diseases named in the same sentence as PFKL in open-access papers (continued):
Sharing a sentence is not in itself a finding about the gene and the disease.
tumor (37 papers, 2013 to 2026). "Knocking down PFKL strongly impeded cell proliferation, to an extent comparable to that caused by TAp73 knockdown, indicating that PFKL also plays a critical role in the proliferation of tumor cells." (PMID 30409970, 2018). "Collectively, these findings demonstrate that upregulation of PFKL is strongly tumorigenic and is likely a major mechanism underlying the effect of TAp73 in tumor cells." (PMID 30409970, 2018). "Yet, the PFKL expression in the tumor blood vessels did associate with the occurrence of lymphovascular invasion and predicted BC recurrence, which was similar to what was found regarding GLUT1 expression, which further reinforces the preponderance of EC metabolism for UBC patients’ prognosis." (PMID 36765947, 2023). "PFKL coordinates diverse aspects of tumor metabolism, including glycolysis, lipid turnover, and functional integration of mitochondria, offering broad opportunities for therapeutic intervention." (PMID 41476787, 2025). "Previous study suggested that glycolytic enzyme PFKL governed lipolysis by promoting LD-mitochondria tethering to enhance β-oxidation and tumor cell proliferation." (PMID 41345683, 2025). "On the other hand, a drug repurposing screen identified an antipsychotic medication, penfluridol, that specifically inhibited PFKL in oesophageal squamous cell carcinoma, suppressing tumour growth and inducing apoptosis." (PMID 40329473, 2025). "YTHDF3 suppressed PFKL mRNA degradation via m6A modification, subsequently promoting tumor growth and lung metastasis of HCC cells." (PMID 40406242, 2025). "PFKL can be activated by TAp73, thereby promoting glycolysis and enhancing cell proliferation in tumor cells." (PMID 41421488, 2025). "In view of the critical role of PFKL in tumor glycolysis, we further investigated the effects of its knockdown on glucose uptake and lactate production." (PMID 38388430, 2024). "FLOT and GMIP are associated with cytoskeletal organization and signal transduction, while PFKL plays a key role in glycolysis, suggesting enhanced metabolic and structural adaptability of platelets in the tumor microenvironment." (PMID 39001461, 2024). "We also verified a novel mechanism for USP14’s involvement in tumor growth and metastasis via its regulation of PFKL." (PMID 38388430, 2024). "While a number of studies have addressed the role of glycolysis in tumor cells, few of these have focused on PFKL and its consequences for tumor progression." (PMID 38388430, 2024). "In this study, we established that the highly expressed DNAAF5 proteins in HCC promote the malignant progression of tumor cells by increasing PFKL protein levels." (PMID 36276075, 2022). "Statistical analysis of quantified images indicated that the differences between tumor and paratumor tissues in A20 protein levels (P < 0.001) and in PFKL protein levels (P < 0.001) were all significant." (PMID 32015333, 2020). "In conclusion, these data suggest that the E3 ligase A20 acts as a tumor suppressor to promote PFKL degradation through UPS, thus suppressing the Warburg effect and inhibiting HCC cell proliferation and metastasis." (PMID 32015333, 2020). "To investigate the role of PFKL in the growth of tumor cells in animals, we injected TAp73+/+ MEFs expressing control vector, and TAp73−/− MEFs expressing vector control or PFKL, to immune-compromised mice." (PMID 30409970, 2018). "Expression of glucose transporters was decreased in three of four BCSC subpopulations relative to tumor, and expression of the glycolytic rate-limiting enzyme phosphofructokinase (PFKL) was decreased in all BCSC subpopulations." (PMID 26316122, 2015).
tumor (continued). "Thus, inhibition of PFKL disrupts both glycolytic flux and lipid metabolism, more effectively inhibiting the tumor bioenergetics." (PMID 41476787, 2025). "Conversely, genes such as FLOT, GMIP, and PFKL showed marked upregulation in tumor samples." (PMID 39001461, 2024). "Notably, our functional rescue experiments suggested that PFKL is a key factor that contributes to USP14’s tumor-promoting roles in OSCC." (PMID 38388430, 2024). "Notably, direct blockade of the glycolytic pathway via 2-DG abolished tumor-promoting effects of PFKL." (PMID 38388430, 2024). "We demonstrated that USP14 specifically interacts with PFKL and enhances its stability through deubiquitination in OSCC cells, which in turn enhances PFKL-mediated glycolytic metabolism, ultimately promoting the proliferation, migration, and tumorigenesis of tumor cells." (PMID 38388430, 2024). "In addition, glucose transporter-1 (GLUT1) and phosphofructokinase-1 (phosphofructokinase-1, liver type, PFKL) are pivotal in the glycolysis of tumor cells." (PMID 35874626, 2022). "Thus, our findings establish A20 as a critical regulator of glycolysis and reveal a novel mechanism for A20 in tumor suppression and PFKL regulation." (PMID 32015333, 2020). "Moreover, the frequent up-regulation of TAp73 likely contributes to increased basal activity of PFK-1 and preferential up-regulation of PFKL over the other isoforms in tumor cells." (PMID 30409970, 2018). "Notably, the overexpression of PFKL in USP14-knockdown HN6 cells could significantly weaken the tumor-suppressing effects induced by depletion of USP14." (PMID 38388430, 2024). "Moreover, upregulation of TAp73 correlates with higher PFKL expression in tumor cells." (PMID 30409970, 2018). "We also found that FGFR4 and related metabolic genes (SLC2A1, LDHA, PFKL) were upregulated in tumors and FGFR4 high-expression groups, suggesting FGFR4's role in tumor metabolism." (PMID 40091020, 2025). "We have found that tumor cells remove metabolons (containing, for example, phospho-Ser226-GLUT1 and PFKL) from their basolateral surface then aggregate the metabolons at the apical surface facing the ductal fluid (milk)." (PMID 36676966, 2022). "We aslo analyzed the differential expression of PGK1, SDHC, PFKL, and NUP43 in tumor and normal samples." (PMID 33584825, 2021). "In tumor cells, the expression of PFK-1 is often upregulated, and the composition of the isoforms changed, with PFKL and PFKP being more highly expressed compared PFKM14." (PMID 30409970, 2018). "To investigate the role of PFKL and G6PD in tumor growth in vivo, we injected control, PFKL-overexpressing, and G6PD-overexpressing HCT116 cells, each with and without TAp73-knockdown, into immune compromised mice." (PMID 30409970, 2018). "In HCC cells exposed to energy stress, PFKL undergoes phosphorylation and interacts with Perilipin 2 (PLIN2) to promote lipid droplet–mitochondria tethering, which facilitates lipolysis and β‐oxidation, supporting tumor proliferation and survival." (PMID 41476787, 2025). "Notably, the high expression of glycolytic key enzymes such as PFKL and GAPFH, downstream of HIF1A, was identified as the driving force behind the increased activation of glycolytic metabolic pathways within tumour cells." (PMID 37994257, 2024). "Our qRT‐PCR experiments further revealed that METTL3 may promote the glycolysis capacity of ESCA cells by upregulating the expression of glycolysis‐related genes SLC2A1, GPI, PFKL, PGK1, ENO1 and PKM, thus facilitating tumour cell proliferation and migration." (PMID 38429907, 2024). "Genes involved in glycolysis (ALDOA, LDHA, PGK1, PFKL, PGM1) and other metabolic processes (GPX4, PRDX4, ACO2, ASPH, IDH2, SQLE, NPC2, SPTSSA) were upregulated in primary tumor cells, suggesting that the metabolism in primary tumors was distinct from that in their matched metastasis." (PMID 39225101, 2024).
tumor (continued). "Real-time qPCR analysis of glucose transporter and glycolytic genes in the xenograft tumor tissues showed that ACE2 overexpression suppressed the mRNA levels of SLC2A1, HK2, ENO1, PFKL, LDHA, and PDK1, while inhibition of Mas receptor with A779 restored the expression of glycolytic components." (PMID 37215979, 2023). "The largest number of changes in gene expression (n = 8) between tumour and non-malignant groups were identified in metabolic genes (PFKL, ATP5A1, UQCRFS1, CPT2, COX5A, ACLY, GPD2, and G6PD)." (PMID 36142793, 2022). "The expression of UBE2D3,p-STAT3, HK-2 and PFKL was reduced in the tumor of the shUBE23D group whereas that of STAT3 exhibited no significant alternation." (PMID 34195079, 2021). "In addition, we found that PFKL expression was significantly lower in NGP and BE2 xenograft tumor-bearing mice treated with DMAMCL than in the control groups." (PMID 34819091, 2021). "Thus, both PFKL and G6PD contribute the proliferative effect of TAp73, and their simultaneous activation by TAp73 likely affords tumor cells a strong advantage during anchorage-independent growth." (PMID 30409970, 2018). "However, in PFKL- or G6PD-overexpressing cells, knocking down TA73 had a minimal effect on tumor growth." (PMID 30409970, 2018). "We also found that mRNA levels of PFKM were similar in ccRCC and non-malignant samples while PFKL was slightly up-regulated in tumor samples." (PMID 27049827, 2016). "Since we had seen that USP14 could promote glucose metabolism in OSCC cells and stabilize PFKL via deubiquitination, we reasoned that USP14 might exert tumor-promoting effects by upregulating the expression of PFKL and enhancing PFKL-mediated glycolysis in OSCC." (PMID 38388430, 2024). "Compared with non-tumor tissues, PFKL protein levels in tumor tissues were generally high." (PMID 36276075, 2022). "The mutations in this tumor included 3 predicted high impact mutations in MTOR a regulator of stress response, OGT a glycosyltransferase that modifies a broad range of targets including H2B, AKT1, EZH2, PFKL, KMT2E/MLL5, MAPT/TAU and HCFC1, and FAM129B a negative regulator of apoptosis." (PMID 28415633, 2017). "The results showed that both PFKL and USP14 protein expression increased in tumor tissues compared to that in their matched adjacent non-cancerous tissues, which exhibited consistent trends." (PMID 38388430, 2024). "The vast majority of well-differentiated and moderately differentiated lesions were negative for PFKL and PKM2 expression, while the only poorly differentiated tumor existing in this study was positive." (PMID 37194791, 2023). "Moreover, upon G6PD or PFKL overexpression in HCT116 cells, knockdown of TAp73 no longer impairs tumor growth in xenograft mouse models." (PMID 30409970, 2018).
cancer (35 papers, 2013 to 2025). A tumor composed of atypical neoplastic, often pleomorphic cells that invade other tissues. "L-phosphofructose kinase (PFKL) glycolysis is the key for the occurrence and progression of tumors, which is associated with the poor prognosis of cancers." (PMID 39669558, 2024). "All three isoforms have been described in human tissues, but the elevated expression of PFKL has been associated with cancer development and aggressiveness, as shown in hepatocellular, lung, and oesophageal malignancies." (PMID 36765947, 2023). "Interestingly, in clinical patients of HCC, q-PCR and Western blot results of fresh surrounding and carcinoma tissues indicated that high expressions of PFKL were largely associated with high expressions of YTHDF3 at both mRNA and protein levels." (PMID 36471428, 2022). "The augmentation of glycolysis, facilitated by PFKL, assumes a crucial role in the malignant advancement of cancer." (PMID 38287371, 2024). "The few (three cases) cancer sections positive for PFKL were large advanced-stage high-grade tumors." (PMID 37194791, 2023). "PFKL plays a fundamental role in glycolysis; its upregulation acts as a turning point in quickly multiplying cancer cells and, most often, its activation fosters proliferation and metastasis via the Warburg effect." (PMID 35409358, 2022). "PFKL acts as a switch for glycolysis in rapidly multiplying cancer cells, and its upregulation boosts the proliferation and metastatic events through the activation of the Warburg effect." (PMID 35053312, 2022). "So far, we conjectured that DNAAF5 exerts its cancer-promoting effects by interacting with PFKL, which promotes the Warburg effect and accelerates the malignant processes of HCC." (PMID 36276075, 2022). "What’s more, we also found that the expression of PFKL is significantly increased in carcinoma tissues in HCC and high expression of PFKL is associated with poor prognosis of HCC patients, supporting the key role of PFKL in HCC suggested by other studies." (PMID 36471428, 2022). "The PFKP isoform, which was induced in MKL1 ΔN200 cells, frequently prevails over PFKM or PFKL in human cancer cells and in the EMT." (PMID 32699630, 2020). "PFKL is a key gene in glycolysis; its high expression serves as a switch for glycolysis in rapidly proliferating cancer cells." (PMID 33233533, 2020). "PFKL activation often promotes proliferation and metastasis through activation of the Warburg effect in cancer cells." (PMID 33233533, 2020). "In rapidly proliferating cancer cells, a high expression level of PFKL serves as a switch for glycolysis." (PMID 32015333, 2020). "The protein level of PFKP was consistently higher in 18 ccRCC samples compared with their adjacent non-malignant kidney tissues, while PFKM and PFKL proteins show comparable levels between normal and cancer groups." (PMID 27049827, 2016). "In cancer cells, PFKL is known to modulate aerobic glycolysis, proliferation, and apoptosis." (PMID 41476787, 2025). "PFK-1, particularly PFKL, exerts a significant influence on glycolysis during cancer progression." (PMID 38287371, 2024). "In addition, glycolytic enzymes such as phosphofructokinase 1(PFK1) and hepatic phosphofructokinase (PFKL) are also regulated by miRNAs in cancer." (PMID 38383342, 2024). "Besides these observation, IHC staining showed that PFKL protein expression in carcinoma tissues was higher than that in surrounding tissues among paraffin sections of 456 HCC patients we collected." (PMID 36471428, 2022). "Considering the critical role of PFK1 in cancer glucose metabolism, we next verified whether PFKL is involved in A20-mediated regulation of HCC progression." (PMID 32015333, 2020). "In HCC, PFKL is the primary expression isoform of PFK1, which promotes aerobic glycolysis and cancer cell proliferation, while inhibiting apoptosis." (PMID 41476787, 2025).
cancer (continued). "While PFKL and PFKM are enriched in liver and muscle, respectively, the third isoform, PFKP, is mainly expressed in platelet and also elevated in most human cancer cells." (PMID 37222403, 2023). "Therefore, PFKP, rather than PFKM and PFKL, is thought to be strongly linked to cancer growth, survival, and metastasis, and could be used as a marker for poor prognosis in cancer." (PMID 36276846, 2022). "Studies have demonstrated that the expression of PFK-1 in cancer cells is often markedly elevated and that the compositions of PFK isozymes are also frequently altered with PFKL and PFKP typically being expressed at higher levels in cancer cells compared with PFKM." (PMID 38388430, 2024). "Notably, however, MUC1-C-dependent, MYC-independent signaling was identified for induction of other genes, such as PFKL, ALDOA, and ENO2, that are essential for driving glycolysis and are upregulated in cancer." (PMID 37915591, 2023). "Indeed, downregulation of several glycolysis genes deeply involved in cancer progression (ENO1, ME1, SLC2A4RG, PFKL and DLAT) was confirmed by RT-qPCR in siRNF40-treated HCC1806 cells." (PMID 37770435, 2023). "The majority of both the non-cancer and the cancer samples were positive for PFKL, PKM2, and pPDH staining." (PMID 36765947, 2023). "Furthermore, we focused on the seven lncRNAs (PFKL, TPD52, ERGIC3, CFL1, CARS, IARS, and H19), which were related to cancer development." (PMID 32485786, 2020). "Besides GLUT1, other key metabolic enzymes (e.g., HK1/2, PFKL, and LDHA) required for the glycolysis pathway of cancer cells were also investigated herein." (PMID 32774674, 2020). "This could be corroborated by our proteomics functional analysis, where we found, for instance, a higher abundance of HADH, PLOD3 and ACAT1 (lysine degradation) and PFKL, NTRK1, PDHB and PDHA1 (central carbon metabolism in cancer) in control piglets compared to UL." (PMID 38409238, 2024).
infection (8 papers, 2018 to 2025). The state of being infected such as from the introduction of a foreign agent such as serum, vaccine, antigenic substance or organism. "To further probe whether PFKL deacetylation at K563 contributes to intimal hyperplasia in vivo, we performed periadventitial infection of adenoviruses encoding PFKL WT, K563Q, or K563R in carotid arteries." (PMID 41421488, 2025). "Phosphofructokinase (PFKL) expression was significantly higher in LVS-infected neutrophils immediately following infection and at 6 hpi." (PMID 35693822, 2022). "Similarly, overexpression of PFKL by the infection of NMCMs with lentivirus expressing Pfkl (lenti-Pfkl) resulted in a hypertrophic growth phenotype." (PMID 36810848, 2023). "Thus, it is tempting to speculate that bacterial lipoproteins and other secreted factors may begin to influence PMN metabolism, including PFKL expression, at the earliest stages of infection." (PMID 35693822, 2022). "Furthermore, gene expression of glycolytic enzymes, lactate, and glutamine metabolism (G6PDH, PKLR, PFKL, LDHA, LDHB, GLS1, GLS2, and GLUL), were upregulated in primary mouse (hACE2) and human hepatocytes upon infection compared to controls." (PMID 35978143, 2022). "Notably, significant induction of PFKL expression was apparent within minutes of LVS addition (0 hpi), reinforcing the notion that F. tularensis can act at a distance and begin to alter neutrophil function at the earliest stages of infection prior to bacterial binding and phagocytosis." (PMID 35693822, 2022).
adenocarcinoma (1 paper, 2025). A common cancer characterized by the presence of malignant glandular cells. "We have previously observed that PFKL–EGFP is recruited to distinct membrane domains in MTLn3 rat adenocarcinoma cells, and we hypothesize that PFKL plays a key role in directional cell migration." (PMID 41159217, 2025).
PFKL also shares sentences with these, for which no sentence is quoted: breast tumor (2 papers); Ascites (1); Cachexia (1); cervical cancer (1); Cirrhosis (1); congenital heart disease (1); COVID-19 (1); diabetes (1); gastric cancer (1); glioblastoma (1); hemorrhoid (1); leukemia (1); lymph node metastasis (1); melanoma (1); oral squamous cell carcinoma (1); prostate carcinoma (1); skin melanoma (1).